TMEM41A (transmembrane protein 41A)
Synonyms: MGC15397; 2900010K02Rik
Tractability: Antibody: UniProt predicts a signal peptide or a membrane-spanning region. PROTAC: ubiquitination databases record sites on it; its protein half-life has been measured.
Gene: Protein-coding gene on chromosome 3 (185,476,496 to 185,499,057, reverse strand). Ensembl gene ENSG00000163900.
Subcellular location: Membrane
Subcellular location (Human Protein Atlas): Nucleoplasm; Cytosol; Golgi apparatus
Gene Ontology:
Molecular function: protein binding
Cellular component: membrane
Genetic constraint (gnomAD): Loss-of-function variants: 20 observed, 24.56 expected, observed/expected ratio (o/e) 0.81, 90% interval 0.57 to 1.18. The upper end of that interval is the gene's LOEUF score, 1.18, which puts it in group 5 of 6, group 1 being the genes least tolerant of losing a copy. Missense variants: 299 observed, 313.73 expected, observed/expected ratio (o/e) 0.95, 90% interval 0.87 to 1.05. Synonymous variants: 133 observed, 137.29 expected, observed/expected ratio (o/e) 0.97, 90% interval 0.84 to 1.12.
Homologues: Orthologues: chimpanzee TMEM41A (99% identical), rabbit TMEM41A (93% identical), pig TMEM41A (92% identical), guinea pig TMEM41A (89% identical), tropical clawed frog tmem41a (65% identical), zebrafish tmem41ab (62% identical), Caenorhabditis elegans Y71A12C.2 (39% identical). Paralogues in human: TMEM41B (29% identical), TMEM64 (22% identical).
Diseases named in the same sentence as TMEM41A in open-access papers:
TMEM41A is named in the same sentence as 8 diseases in open-access papers, as found by Europe PMC text mining. Sharing a sentence is not in itself a finding about the gene and the disease. The quoted sentences say what the papers report.
colorectal cancer (1 paper, 2023). A primary or metastatic malignant neoplasm that affects the colon or rectum. "In vitro and in vivo studies found that SPRING1 could enhance the growth of colorectal cancer cells, which was related to the increased expression of TMEM41A." (PMID 37478120, 2023). "Studies have shown that the SPRING1 could enhance colorectal cancer cell growth by promoting TMEM41A expression." (PMID 37478120, 2023). "Recent studies have shown the association between transmembrane protein 41A (TMEM41A) and the occurrences and developments of gastrointestinal tumors, with significantly higher expression levels of SREBF pathway regulator in golgi 1 (SPRING1) in colorectal cancer than in adjacent normal tissues." (PMID 37478120, 2023).
diabetes (1 paper, 2023). "Specifically, TMEM41A overexpression was associated with shorter OS in patients with EC with stages I, I-II, I-III, and III, body weight ≤ 80kg, or > 80kg, height, BMI, G2-3 grade, endometrioid, tumor invasion, age ≥ 60 years, hormone therapy (no), radiotherapy (no), diabetes (yes or no)." (PMID 37478120, 2023). "Similarly, TMEM41A overexpression was associated with shorter DSS in patients with EC with stages I, I-II, I-III, II-III, II-IV, and III, weight ≤ 80 or > 80kg, height, BMI, G2-3 grade, endometrioid, tumor invasion, age > 60 years, hormone therapy (no), radiotherapy (no), diabetes (yes or no)." (PMID 37478120, 2023).
endometrial carcinoma (1 paper, 2023). A malignant tumor arising from the epithelium that lines the cavity of the uterine body. "However, the association between TMEM41A expression and endometrial carcinoma (EC) remains unclear." (PMID 37478120, 2023).
gastric cancer (1 paper, 2023). A primary or metastatic malignant neoplasm involving the stomach. "TMEM41A is also associated with lymph node metastasis, distant metastasis, and poor prognosis in patients with gastric cancer." (PMID 37478120, 2023). "TMEM41A was strongly expressed in gastric cancer and linked to lymph node metastasis, distant metastasis, late stage, and poor prognosis." (PMID 37478120, 2023). "Inhibition of TMEM41A expression could reduce gastric cancer cell migration and metastasis by inhibiting the epithelial-mesenchymal transformation (EMT) process and autophagy." (PMID 37478120, 2023). "Inhibition of TMEM41A expression could delay gastric cancer cell metastasis by regulating EMT and autophagy." (PMID 37478120, 2023).
cancer (3 papers, 2021 to 2024). A tumor composed of atypical neoplastic, often pleomorphic cells that invade other tissues. "TMEM41A overexpression was associated with stromal, immune, and estimate scores of cancer samples." (PMID 37478120, 2023). "Our future studies would focus on collecting cancer tissues and normal adjacent tissues from patients with EC to verify the expression of TMEM41A and explore its impact on the prognosis of patients with EC." (PMID 37478120, 2023). "Expression levels of transmembrane protein 41A (TMEM41A) are related to the progression of malignant tumors." (PMID 37478120, 2023). "TMEM41A was strongly expressed in cancer tissues of patients with G2 and G3 stages compared with those of G1 stage and in cancer tissues of G3 patients compared with the G2 patients." (PMID 37478120, 2023). "Specifically, TMEM41A was strongly expressed in cancer tissues from patients with clinical stage II, III, and IV EC compared with those of clinical stage I." (PMID 37478120, 2023). "Furthermore, TMEM41A was strongly expressed in cancer tissues of patients above 60 and those with a weight greater than 80 kg." (PMID 37478120, 2023). "Therefore, this study aims to comprehensively analyze the roles and possible mechanisms of TMEM41A in EC and to identify potential candidate molecules for cancer treatment." (PMID 37478120, 2023). "Notably, TMEM41A expression levels were significantly enhanced in cancer tissues from deceased patients compared to those from living patients." (PMID 37478120, 2023). "In addition, TMEM41A was strongly expressed in serous patient carcinoma tissues compared to patients with mixed subtypes." (PMID 37478120, 2023). "Interestingly, some novel BC related proteins (STEAP4, CLPTM1L, TMEM41A, DHCR24, etc.) were also discovered, which have been reported to be involved in other cancer types." (PMID 33842315, 2021). "Furthermore, NBDep identified two putative non-missense driver genes MEPCE and TMEM41A that were not previously known to be cancer driver genes." (PMID 38195844, 2024).
tumor (1 paper, 2023). "Overexpression of TMEM41A was associated with clinical stage, age, weight, histological subtype, tumor grade, and survival status of patients with EC." (PMID 37478120, 2023). "We found that TMEM41A overexpression was correlated with EC stromal, immune, and estimate scores and was linked with tumor purity, immune cells (such as the macrophages, CD8 T cells, and TFH), and immune cell markers (such as the CD8A, CD3D, and CD3E)." (PMID 37478120, 2023). "Clinical stage, age, tumor grade, radiotherapy, and TMEM41A overexpression were factors of poor prognosis in patients with EC." (PMID 37478120, 2023). "Our comprehensive analysis revealed that TMEM41A overexpression was associated with shorter OS, clinical stage, age, DSS, weight, histological subtype, PFI, tumor grade, race, and menopausal status in patients with EC." (PMID 37478120, 2023). "Additionally, we found that TMEM41A overexpression correlated with tumor purity, CD8+ T cells, macrophage, and neutrophil levels, and with the copy numbers of CD8+ T cell, neutrophil, and DC in the TIMER database." (PMID 37478120, 2023).
TMEM41A also shares sentences with these, for which no sentence is quoted: gastrointestinal tumors (1 paper); lymph node metastasis (1).